IRF5 (interferon regulatory factor 5)
Description:
Transcription factor that plays a critical role in innate immunity by activating expression of type I interferon (IFN) IFNA and INFB and inflammatory cytokines downstream of endolysosomal toll-like receptors TLR7, TLR8 and TLR9. Regulates the transcription of type I IFN genes (IFN-alpha and IFN-beta) and IFN-stimulated genes (ISG) by binding to an interferon-stimulated response element (ISRE) in their promoters (By similarity). Can efficiently activate both the IFN-beta (IFNB) and the IFN-alpha (IFNA) genes and mediate their induction downstream of the TLR-activated, MyD88-dependent pathway (By similarity). Key transcription factor regulating the IFN response during SARS-CoV-2 infection.
Synonyms: IRF-5; SLEB10
Tractability: PROTAC: UniProt records ubiquitination sites on it; ubiquitination databases record sites on it; its protein half-life has been measured.
Gene: Protein-coding gene on chromosome 7 (128,933,429 to 128,950,038, forward strand). Ensembl gene ENSG00000128604.
Subcellular location: Cytoplasm; Nucleus
Pathways (Reactome):
Immune System: Interferon alpha/beta signaling; Interferon gamma signaling; SLC15A4:TASL-dependent IRF5 activation
Gene Ontology:
Molecular function: DNA-binding transcription activator activity, RNA polymerase II-specific; DNA-binding transcription factor activity, RNA polymerase II-specific; identical protein binding; protein binding; protein kinase binding; protein serine/threonine kinase binding; sequence-specific DNA binding; sequence-specific double-stranded DNA binding; RNA polymerase II cis-regulatory region sequence-specific DNA binding; DNA-binding transcription factor activity; transcription cis-regulatory region binding
Biological process: cellular response to muramyl dipeptide; cellular response to peptidoglycan; cellular response to virus; cytokine-mediated signaling pathway; nucleotide-binding oligomerization domain containing 2 signaling pathway; positive regulation of apoptotic process; positive regulation of cytokine production involved in immune response; positive regulation of interferon-alpha production; positive regulation of interferon-beta production; positive regulation of interleukin-12 production; positive regulation of transcription by RNA polymerase II; positive regulation of type I interferon production; toll-like receptor 9 signaling pathway; immune system process; innate immune response; regulation of transcription by RNA polymerase II; defense response to virus; regulation of DNA-templated transcription
Cellular component: cytoplasm; nucleus; chromatin; cytosol; nucleoplasm
Genetic constraint (gnomAD): Loss-of-function variants: 19 observed, 52 expected, observed/expected ratio (o/e) 0.37, 90% interval 0.25 to 0.54. The upper end of that interval is the gene's LOEUF score, 0.54, which puts it in group 2 of 6, group 1 being the genes least tolerant of losing a copy. Missense variants: 486 observed, 661.29 expected, observed/expected ratio (o/e) 0.73, 90% interval 0.68 to 0.79. Synonymous variants: 251 observed, 261.15 expected, observed/expected ratio (o/e) 0.96, 90% interval 0.87 to 1.07.
Homologues: Orthologues: chimpanzee IRF5 (99% identical), macaque IRF5 (95% identical), pig IRF5 (89% identical), dog IRF5 (89% identical), rat Irf5 (86% identical), mouse Irf5 (85% identical), rabbit IRF5 (84% identical), guinea pig IRF5 (83% identical), tropical clawed frog irf5 (58% identical), zebrafish irf5 (53% identical). Paralogues in human: IRF6 (46% identical), IRF4 (27% identical), IRF3 (25% identical), IRF8 (25% identical), IRF7 (21% identical), IRF9 (21% identical), IRF2 (16% identical), IRF1 (14% identical).
Diseases named in the same sentence as IRF5 in open-access papers:
IRF5 is named in the same sentence as 220 diseases in open-access papers, as found by Europe PMC text mining. Sharing a sentence is not in itself a finding about the gene and the disease. The quoted sentences say what the papers report.
systemic lupus erythematosus (113 papers, 2007 to 2026). An autoimmune multi-organ disease typically associated with vasculopathy and autoantibody production. "Genetic polymorphisms within or near the IRF5 locus have been associated with IRF5 hyperactivation and the dysregulation of IRF5 activity has been implicated in the pathogenesis of systemic lupus erythematosus (SLE)." (PMID 40639948, 2025). "Genetic variants in IRF5 that reduce its expression are associated with decreased susceptibility to UC and other immune-mediated diseases, such as systemic lupus erythematosus (SLE), rheumatoid arthritis, and primary biliary cirrhosis." (PMID 41007813, 2025). "While IRF1, IRF3, IRF5, and IRF8 predominantly exacerbate AS, context-dependent roles (e.g., IRF5 in lupus-associated AS) highlight their therapeutic complexity." (PMID 40980176, 2025). "Whereas dysregulation of IRF5 activity has been implicated in the development of numerous autoimmune diseases including systemic lupus erythematosus, the factors that modulate TLR-induced IRF5 post-translational modifications are poorly understood." (PMID 40639948, 2025). "Lupus risk loci for the majority of these IRF5 causal candidates are associated with increased total IRF5 expression in blood and lymphoblastoid cell lines, except for rs729302-A where results are contradictory." (PMID 39624492, 2024). "With the evident genetic association of the SLC15A4/TASL/IRF5 module with lupus, feeblin represents an encouraging strategy for targeting an etiological mechanism." (PMID 37863876, 2023). "This type of IRF5 polymorphism has been generally associated with ADs, such as systemic lupus erythematosus, rheumatoid arthritis, inflammatory bowel diseases and multiple sclerosis." (PMID 36534351, 2023). "We previously reported that heterozygous deficiency of IRF5 reduces disease in the FcγRIIB−/−Yaa mouse lupus model." (PMID 34197340, 2021). "We now show that monoallelic IRF5 deficiency in B cells markedly reduced disease in a murine lupus model." (PMID 34197340, 2021). "IRF5 polymorphisms have been associated with the presence of coronary artery calcium in patients with systemic lupus erythematosus." (PMID 33802675, 2021). "In an animal model of IRF5-deficient systemic lupus erythematosus, an increase in atherosclerosis was observed." (PMID 33802675, 2021). "Global homozygous or heterozygous deficiency of IRF5 markedly reduces disease severity in mouse lupus models." (PMID 34197340, 2021). "Subsequently, it was demonstrated that global heterozygous deficiency of IRF5 also reduces disease in the Lyn-deficient mouse lupus model, the gld.apoE-deficient mouse lupus model, and in the Swap70-deficient Def6-deficient mouse lupus model." (PMID 34197340, 2021). "To examine the role of B cell–specific IRF5, we conditionally deleted 1 allele of IRF5 in the FcγRIIB−/−Yaa mouse lupus model, the model we previously used to demonstrate the effect of global homozygous and heterozygous IRF5 deletion." (PMID 34197340, 2021). "Gain-of-function polymorphisms in the transcription factor IFN regulatory factor 5 (IRF5) are associated with an increased risk of developing systemic lupus erythematosus." (PMID 34197340, 2021). "Of note, models of systemic lupus erythematosus have shown the uptake of complement associated antigen by follicular DCs generates type 1 IFN in an IRF-5 dependent pathway." (PMID 34249009, 2021). "Multiple models of murine lupus have shown that loss of Irf5 is protective against disease development." (PMID 32582209, 2020). "In human, IRF5 gene polymorphisms are associated with several inflammatory and autoimmune diseases including systemic lupus erythematosus (SLE), inflammatory bowel disease, and rheumatoid arthritis." (PMID 33362784, 2020). "Hyperactivation of IRF5 has been implicated in numerous autoimmune diseases, chief among them systemic lupus erythematosus (SLE)." (PMID 32582209, 2020).
systemic lupus erythematosus (continued). "The importance of IRF5 for lupus pathogenesis was also demonstrated by the attenuation of the disease in mouse models deficient of IRF5, which was accompanied with decreased activated CD4+ T cells and autoantibodies." (PMID 30061896, 2018). "Interferon regulatory factor 5 (IRF5) is widely recognized as a risk locus for systemic lupus erythematosus (SLE)." (PMID 29867973, 2018). "A common finding between the different models of murine lupus that lack Irf5 is the significant decrease in pathogenic autoantibody secretion suggesting a role for IRF5 in B cells." (PMID 29367853, 2017). "IRF5 proved to be associated with some autoimmune diseases like systemic lupus erythematosus and rheumatoid arthritis." (PMID 28562332, 2017). "Genome-wide association studies have implied the association of IRF5 with several autoimmune diseases, including systemic lupus erythematosus (SLE), Sjogren’s syndrome, inflammatory bowel disease and multiple sclerosis." (PMID 28578407, 2017). "IRF5 has previously been linked to IgG isotype secretion in mice, with Irf5−/− mice having reduced IgG2a levels following viral infection and in murine models of lupus." (PMID 29367853, 2017). "IRF5-deficient cDC exhibited a reduced ability to produce TNFα, IL-6, and IL-10 in lupus-prone mice." (PMID 27034965, 2016). "Since the first study characterising IRF5 it has been associated with systemic lupus erythematosus and plays an important role in controlling type I IFN expression." (PMID 25856589, 2015). "Interferon regulatory factor 5 (IRF5) polymorphisms are strongly associated with an increased risk of developing the autoimmune disease systemic lupus erythematosus." (PMID 25076492, 2014). "IRF5 is a genetic risk factor for many autoimmune diseases, including systemic lupus erythematosus, rheumatoid arthritis, multiple sclerosis, and inflammatory bowel disease." (PMID 25159141, 2014). "In mouse lupus models, IRF5-deficiency was shown to reduce disease severity consistent with an important role for IRF5 in disease pathogenesis." (PMID 25076492, 2014). "We found that IRF5 was critical for disease development in the FcγRIIB−/−Yaa and FcγRIIB−/− lupus models as IRF5-deficient FcγRIIB−/−Yaa and FcγRIIB−/− mice developed minimal disease manifestations." (PMID 25076492, 2014). "Polymorphisms in IRF5 have been shown to be associated with the autoimmune disease Systemic Lupus Erythematosus (SLE) and other autoimmune conditions, suggesting a central role for IRF5 in the regulation of the immune response." (PMID 25084355, 2014). "Polymorphisms in the transcription factor interferon regulatory factor 5 (IRF5) have been strongly associated with an increased risk of developing lupus in multiple human genetic studies." (PMID 25076492, 2014). "Polymorphisms in the interferon regulatory factor 5 (IRF5) gene are associated with susceptibility to systemic lupus erythematosus, rheumatoid arthritis and other diseases through independent risk and protective haplotypes." (PMID 23941291, 2013). "Consistent observations in murine models of lupus indicate that loss of Irf5 protects mice from lupus-like disease." (PMID 23349905, 2013). "Fine mapping studies now underway suggest that there are two independent associations with IRF5 defining risk for lupus (L. Kottyan, J. Harley, K.M. Kaufman, unpublished data)." (PMID 22909381, 2012). "In current study, we showed evidence for gene–gene interaction between the 2 independent lupus-associated SNPs within the IRF5 and IKZF1 (AP = 0.41, RERI = 0.93)." (PMID 23236436, 2012). "Several haplotypes of these IRF5 variants were associated with distinct risks to human lupus and Wegener’s granulomatosis." (PMID 23028731, 2012). "Interferon regulatory factor 5 (IRF5), a risk factor for systemic lupus erythematosus, is activated in response to pathogen recognition receptor engagement and downstream effector molecules." (PMID 22412986, 2012).
systemic lupus erythematosus (continued). "An allele in IRF5 has been reported as conferring an increased risk for inflammatory bowel diseases, systemic lupus erythematosus and MS, suggesting that there is a link between IRF5 and several autoimmune diseases." (PMID 21152067, 2010). "Previously, IRF5 has been found to be associated with systemic lupus erythematosus, rheumatoid arthritis and inflammatory bowel diseases." (PMID 18285424, 2008). "IRF7 was recently reported to be the master regulator of IFN type I-dependent immune responses, and recent publications have shown that an IRF5 polymorphism is strongly associated with systemic lupus erythematosus (SLE)." (PMID 17490473, 2007). "Conversely, as in the case of viral infections, we do not expect the SLC15A4-TASL complex to be involved in TLR7/9- and IRF5-independent autoinflammatory and autoimmune models, such as the lupus-like manifestations observed upon TREX1-deficiency which relies on the STING pathway." (PMID 39856058, 2025). "Besides gout, genetic variants in IRF5 were already associated with systemic lupus erythematosus, rheumatoid arthritis, Sjogren syndrome, and other inflammatory diseases." (PMID 41155224, 2025). "Notably, the activation of IRF5 and ISGs in the active and remission phases of SLE suggests that the therapeutic effects of inhibiting IRF5 are better than those of full inhibition of IFN-I signaling in Lyn-deficient lupus mice." (PMID 39478861, 2024). "Polymorphisms in IRF5 have been associated with multiple autoimmune diseases, particularly in systemic lupus erythematosus (SLE), primary Sjögren syndrome, and rheumatoid arthritis, which are characterized by significant sex differences in the disease prevalence." (PMID 36814288, 2023). "An enhancer variant rs4728142, affecting IRF5 expression and causal in the association with systemic lupus erythematosus, is also in high linkage disequilibrium with some of the SNPS we studied (r2=0.71 both with rs4731532 and rs3807306 in European populations)." (PMID 37978231, 2023). "Moreover, IRF5 has been associated with susceptibility to different inflammatory and autoimmune diseases including rheumatoid arthritis, systemic lupus erythematosus, multiple sclerosis, and Sjörgen’s syndrome." (PMID 36155972, 2022). "Notably, global homozygous or heterozygous deficiency of IRF5 has conferred protection in many mouse models of lupus." (PMID 34197340, 2021). "In addition, IRF5 polymorphisms are known to be associated with multiple chronic inflammatory disorders, including systemic lupus erythematosus (SLE), Sjögren Syndrome (SS), and rheumatoid arthritis (RA)." (PMID 34065953, 2021). "Because B cells, mDCs, pDCs, and monocytes/macrophages have all been implicated in lupus pathogenesis, it is plausible that IRF5 in any 1 or more of these cell types may be required for disease pathogenesis." (PMID 34197340, 2021). "Autoimmunity in these individuals could plausibly have been ascribed to predicted-damaging RFP variants in genes with strong associations to lupus (IRF5, LILRB3) or autoimmune hepatitis (C4A)." (PMID 31307400, 2019). "Previous work has shown that production of IFN in anti-Ro+ individuals is associated with the lupus risk variant of IRF5, and thus these individuals may lack genetic variants that promote IFN production." (PMID 28245862, 2017). "SLC15A4-, MyD88-, IRF8-, or IRF5-deficient lupus-prone mice have shown ameliorated lupus symptoms with reduced IFNα protein level in the serum, decreased IFNα transcript level in pDC, downregulation of type I IFN inducible genes, and suppressed activation of both T cells and B cells." (PMID 27034965, 2016). "We had previously found that in the FcγRIIB−/−Yaa and FcγRIIB−/− lupus models, the IRF5 heterozygotes were markedly protected from disease and exhibited a phenotype similar to the IRF5-deficient mice, even though IRF5 protein expression was still approximately 40% of the wildtype level." (PMID 25076492, 2014).
systemic lupus erythematosus (continued). "As DOCK2 regulates lymphocyte trafficking and Toll-like receptor signaling, this raised the possibility that some of the protective effects attributed to IRF5 deficiency in the mouse lupus models may instead have been due to DOCK2 deficiency." (PMID 25076492, 2014). "The effect of IRF5 deficiency in the MRL/lpr lupus model was reported before the DOCK2 mutation was discovered and no information is available as to whether the DOCK2 mutation was present in the experimental mice in that study." (PMID 25076492, 2014). "As IgG2a, IgG2b and IgG3 are all pathogenic isotypes in murine lupus, IRF5 deficiency may ameliorate lupus at least in part through reduction of B cell antibody production." (PMID 25076492, 2014). "Taken together with the human genetic data showing that gain-of-function polymorphisms of IRF5 are associated with an increased risk of developing lupus, this suggests that IRF5 may be a useful therapeutic target in lupus." (PMID 25076492, 2014). "IRF5 has been implicated in various autoimmune diseases, including multiple sclerosis and systemic lupus erythematosus (SLE)." (PMID 41007813, 2025). "Accumulating studies indicate that multiple polymorphisms of the IRF5 gene are involved in autoimmune diseases, such as rheumatoid arthritis (RA), systemic lupus erythematosus (SLE), and IBD." (PMID 35967345, 2022). "Furthermore, the fact that heterozygous global deletion of IRF5 markedly reduces disease in lupus models suggested that loss of 1 allele of IRF5 in B cells might confer protection." (PMID 34197340, 2021). "The transcription factor IRF5 has been implicated as a therapeutic target for the autoimmune disease systemic lupus erythematosus (SLE)." (PMID 34282144, 2021). "In systemic lupus erythematosus (SLE), IRF5 genetic variants are associated with an increased risk to develop the disease, alongside elevation of IRF5 expression and IFN production." (PMID 30795559, 2019). "Genetic variants that affect isoform usage have been associated with immune disorders, including single-nucleotide polymorphisms (SNPs) that alter the relative splicing of two IRF5 isoforms associated with systemic lupus erythematosus (SLE)." (PMID 30446528, 2018). "For example, the highly connected TF IRF5 is associated with multiple autoimmune diseases, including multiple sclerosis and systemic lupus erythematosus (SLE), and leads to low type-I interferon, TNF and IL6 production in knockout mice." (PMID 30184180, 2018). "Rs2004640, the first single-nucleotide polymorphism (SNP) to be identified, is closely associated with the elevated expression of multiple isoforms of IRF5 and is an important genetic risk factor for systemic lupus erythematosus (SLE)." (PMID 28525378, 2017). "Additionally, IRF5 is also linked to autoimmune responsivity through its association to lupus." (PMID 27934696, 2016). "Polymorphisms in the interferon regulatory factor 5 (IRF5) gene have been consistently replicated and shown to confer risk for or protection from the development of systemic lupus erythematosus (SLE)." (PMID 23349905, 2013). "IRF5 cisSNP rs4728142 is associated with both cerebellar IRF5 levels and risk of systemic lupus erythematosus (SLE)." (PMID 22685416, 2012). "Interferon regulatory factor 5 (IRF5) is an autoimmune susceptibility factor associated with increased risk of human systemic lupus erythematosus (SLE)." (PMID 22412986, 2012). "Recently, two studies provided convincing evidence that IFN regulatory factor 5 (IRF5) gene polymorphisms are significantly associated with systemic lupus erythematosus (SLE) in several white populations." (PMID 17389033, 2007). "Recently, two studies provided convincing evidence that IFN regulatory factor 5 (IRF5 [MIM 607218]) gene polymorphisms are significantly associated with systemic lupus erythematosus (SLE [MIM 152700])." (PMID 17389033, 2007).